ENSG00000283952 (novel protein)
Gene: Protein-coding gene on chromosome 1 (211,082,872 to 211,188,533, reverse strand). Ensembl gene ENSG00000283952.
Genetic constraint (gnomAD): Loss-of-function variants: 5 observed, 11.33 expected, observed/expected ratio (o/e) 0.44, 90% interval 0.23 to 0.93. Missense variants: 57 observed, 94.03 expected, observed/expected ratio (o/e) 0.61, 90% interval 0.49 to 0.76. Synonymous variants: 20 observed, 29.57 expected, observed/expected ratio (o/e) 0.68, 90% interval 0.47 to 0.98.